GAU1 (GALNT8 antisense upstream 1)
Synonyms: GALNT8-DT
Gene: Long non-coding RNA gene on chromosome 12 (4,700,417 to 4,720,102, reverse strand). Ensembl gene ENSG00000255474.
Diseases named in the same sentence as GAU1 in open-access papers:
GAU1 is named in the same sentence as 7 diseases in open-access papers, as found by Europe PMC text mining. Sharing a sentence is not in itself a finding about the gene and the disease. The quoted sentences say what the papers report.
retinoblastoma (4 papers, 2020 to 2025). A malignant tumor that originates in the nuclear layer of the retina. "GAU1, which was initially discovered and named in our prior research, was first identified in neuroblastoma and retinoblastoma." (PMID 38782895, 2024). "LncRNA GAU1 overexpression in retinoblastoma cisactivates the expression of its target gene GALNT8 to induce retinoblastoma tumorigenesis." (PMID 32366932, 2020). "According to the previous report that GAU1 and GALNT8 share a cisregulation relationship in retinoblastoma and the mutual promoter region of the two genes, investigation on the mechanism behind the abnormal promoter activation in CRC should be conducted in our future studies." (PMID 34239555, 2021).
colorectal cancer (1 paper, 2021). A primary or metastatic malignant neoplasm that affects the colon or rectum. "Then, we further experimentally quantified the GAU1 mRNA overexpression in human colorectal cancer cell lines SW620, HCT116, DLD1, and LoVo versus human intestinal epithelial cell line NCM460 (P < 0.05)." (PMID 34239555, 2021).
colorectal tumors (1 paper, 2024). "By using our IDTR approach, we showed for the first time that oncolytic adenovirus H101 could reactivate silenced cGAS, while silencing GAU1 long noncoding RNA (lncRNA) inhibited NF-κB p65 overactivation, resulting in efficient in vitro and in vivo antitumor efficacy in colorectal tumors." (PMID 38782895, 2024).
tumor (3 papers, 2021 to 2024). "Next, we tested the ability of tumor cells to form colonies in vitro using a classic colony formation assay after combined treatment with GAU1 knockdown and H101 infection." (PMID 38782895, 2024). "We found that the GAU1 lncRNA was highly expressed in SW620 and LOVO tumor cells." (PMID 38782895, 2024). "However, mice that received the combined treatment of GAU1 ASO and H101 demonstrated a notably greater reduction in tumor growth (n = 5, *P < 0.05) than those subjected to treatment administered individually, and the overall inhibition rate of tumor growth was approximately 88%." (PMID 38782895, 2024). "The strong expression correlation between GAU1 and GALNT8 was further validated in our 66 pairs of clinical samples (P < 10−4), with a significant upregulation of GALNT8 expression in the tumor tissues (T) compared with the adjacent nontumorous tissues (N) (P < 10−4)." (PMID 34239555, 2021).
cancer (1 paper, 2021). A tumor composed of atypical neoplastic, often pleomorphic cells that invade other tissues. "Together with the experimental evidence overexpression or silencing GALNT8 mimicked the cancer cell line phenotypic alteration after GAU1 overexpression or knockout." (PMID 34239555, 2021). "Our result showed an oxaliplatin hypersensitivity in cancer cell lines overexpressing GAU1/GALNT8." (PMID 34239555, 2021). "Furthermore, qRT-PCR of GAU1 mRNA in 66 pairs of CRC tissues and adjacent normal tissues also confirmed GAU1 as the cancer-specific lncRNA in CRC (P = 2.53 × 10−2)." (PMID 34239555, 2021). "The in vitro oxaliplatin drug response data revealed that cancer cells overexpressing GAU1 or GALNT8 are more vulnerable to chemotherapy agents causing replication fork collapse, indicating GAU1/GALNT8 axis as a potential actionable target for the personalized medicine of CRC." (PMID 34239555, 2021). "By integrating the differential expression data from 7,256 curated RNA-Seq libraries in MiTranscriptome and experimental validation, we demonstrated that GAU1, together with its downstream protein GALNT8, is associated with cancer cell proliferation, poor patient survival, and chemotherapy response." (PMID 34239555, 2021).
infection (1 paper, 2024). The state of being infected such as from the introduction of a foreign agent such as serum, vaccine, antigenic substance or organism. "As expected, we observed significant inhibition of cell growth at 72–120 hours following the combined treatment of GAU1 knockdown and H101 infection." (PMID 38782895, 2024). "Western blot assays demonstrated that H101 infection did not change the expression of NF-κB p65 (Lane 2 and Original full length western blots image 4) compared to GAU1 knockdown-induced NF-κB p65 inhibition (Lanes 3 and 4 and Original full length western blots image 4) in SW620 cells." (PMID 38782895, 2024).
GAU1 also shares sentences with these, for which no sentence is quoted: neuroblastoma (1 paper).